EGFR (epidermal growth factor receptor)
Diseases named in the same sentence as EGFR in open-access papers (continued):
Sharing a sentence is not in itself a finding about the gene and the disease.
melanoma (continued). "Beyond pyrexia, rash and photosensitivity—common dermatologic toxicities—have been analogized in other kinase inhibitor settings (e.g., EGFR inhibitors) as correlates of adequate target inhibition, though direct evidence in melanoma/triose MAPK contexts remains limited." (PMID 41374434, 2025). "Yet to be addressed is the understanding of whether cSRS remains necessary in completely resected patients who have targeted therapy or immunotherapy options, such as those with melanoma or epidermal growth factor receptor (EGFR)-positive NSCLC." (PMID 40922838, 2025). "However, in melanoma cells that harbor a BRAF V600E mutation, expression of EGFR ranges from a low of 0.8 up to 3.1 which is well above the expected expression levels of EGFR." (PMID 40869231, 2025). "Additionally, advanced salvage options—such as repeat SRS and systemic therapies effective for intracranial and extracranial disease (e.g., melanoma and NSCLC with EGFR mutations or ALK translocations)—challenge the routine use of WBRT." (PMID 41296115, 2025). "Specifically, the expression of METTL3 is upregulated in PLX4032-resistant melanoma cells, increasing m6A modification on EGFR mRNA, which in turn promotes EGFR protein translation efficiency, ultimately causing melanoma cells to become resistant to PLX4032 targeted therapy." (PMID 41584846, 2025). "Similarly, another study suggested that antibiotic use was associated with reduced TKI efficacy in advanced melanoma and NSCLC, but the TKI cohort also included both EGFR and BRAF inhibitors, precluding class-specific conclusions." (PMID 41294692, 2025). "This is notably evident in BRAF V600E mutations, where response to treatment varies by tumor type—requiring monotherapy in some cancers, a combination with MEK inhibitors in melanoma, and a combination with EGFR inhibitors in CRC to counteract feedback activation pathways and inherent resistance." (PMID 40576713, 2025). "EGFR is a well-established marker in multiple cancers, including melanoma." (PMID 41516067, 2025). "Furthermore, we demonstrated that differential expression of all investigated Ibrutinib target genes (i.e., BTK, EGFR, ERBB2, ITK, JAK3, and TEC) is associated with apoptotic mechanisms in clinical melanoma samples." (PMID 38790974, 2024). "Moreover, experiments with EGFR-expressing BLM melanoma cells have shown that cetuximab can reduce invasiveness without compromising cell viability or growth." (PMID 38534309, 2024). "Overall, AC-EO is involved in the inhibition of EGFR signaling and may be a therapeutic agent against melanoma." (PMID 38791435, 2024). "Moreover, melanoma cell lines with higher EGFR expression are more prone to becoming resistant to vemurafenib than cells with lower EGFR expression." (PMID 38396984, 2024). "Moreover, expression of some RTK family receptors is raised in these cells, while the level of HER3 was reduced, what, together with elevated EGFR level, is characteristic of the invasive subtype of BRAFi-resistant melanoma cells." (PMID 39175042, 2024). "Furthermore, EGFR expression in melanoma has been positively correlated with a poor prognosis for survival." (PMID 38534309, 2024). "As targeted anti-EGFR therapy has shown promising results in decreasing melanoma cell growth and hindering its invasive abilities, we examined melanomas and their precursors for mutations that lead to the constitutive activation of kinase activity, such as exon 19 deletions (Del19)." (PMID 38396984, 2024). "We identified epidermal growth factor receptor (EGFR), human epidermal growth factor receptor 2 (HER2), melanoma-associated chondroitin sulfate proteoglycan (MCSP), and programmed death ligand 1 (PD-L1) as being expressed by A375 tumor cells and by established tumors." (PMID 38828721, 2024).
melanoma (continued). "Our results obtained in humanized mice are consistent with the observation that cetuximab may exert some degree of therapeutic efficacy in vivo against BRAFi-responsive melanoma cells favored by a low basal level of EGFR expression." (PMID 38510242, 2024). "Additionally, CAP and epidermal growth factor receptor (EGFR) inhibitor had an additive anticancer effect in a CAP-resistant melanoma cell line." (PMID 37241912, 2023). "In malignant melanoma, EGFR up-regulated PD-L1 through the EGFR/STAT3 pathway." (PMID 37420173, 2023). "It has been reported that KIF22 activates EGFR signaling, an effective target for melanoma." (PMID 37944197, 2023). "In addition, the possible therapeutic role of combined treatment with CAP and EGFR inhibitors was assessed in melanomas." (PMID 37241912, 2023). "Similarly, in a study on the heterogeneity of melanoma cell lines and tumors, AR expression was found to cluster together with EGFR and SERPINE1 in an undifferentiated AXL positive subgroup connected with targeted drug resistance." (PMID 37838724, 2023). "Our findings suggest that cinobufagin may affect melanoma by arresting the cell cycle by inhibiting three protein tyrosine/serine kinases (EGFR, ERBB2, and CDK2)." (PMID 38348352, 2023). "Moreover kinase profiling conducted in a panel of melanoma cell strains showed that EGFR is often activated in melanoma cells." (PMID 37679999, 2023). "However, abnormal expression and dysregulated activities of EGFR drive the development of cancers in the lung, breast, prostate, colon, skin (melanoma), and others." (PMID 37333807, 2023). "Moreover, herbacetin inhibited the angiogenesis of melanoma cells by blocking the EGFR signaling pathway, inhibiting the ERK and AKT’s phosphorylation." (PMID 36829966, 2023). "Thus, increased AR expression in melanoma cells elicits changes found in a BRAFi-tolerant subpopulation and enhanced EGFR and SERPINE1 expression of likely clinical significance." (PMID 37838724, 2023). "Nevertheless, the in vitro and in vivo evidence supporting the use of ERBBi in melanoma is strong, and further investigation into their use in melanoma patients with high levels of EGFR expression is warranted, particularly given the evidence for its role in driving anoikis resistance." (PMID 37181747, 2023). "Interestingly, BRAF mutant CRCs exhibit elevated levels of phosphor-EGFR compared to BRAF mutant melanomas." (PMID 38111008, 2023). "Hence, Nrf2 indirectly derepresses the EGFR, contributing in the maintenance of EGFR-expressing melanomas." (PMID 36747120, 2023). "Moreover, EGFR expression in melanomas was reported to influence the sentinel lymph node metastasis and EGFR amplification was related to the weak response of patients with mucosal and acral melanoma to immune checkpoint inhibitors based therapy." (PMID 37679999, 2023). "Although EGFR expression and its role in melanoma are conflicting, the clinical significance of EGFR has been suggested in the literature, especially in advanced or distant metastatic melanoma, a debilitating cutaneous cancer with aggressive behavior and a poor prognosis." (PMID 37241912, 2023). "The authors revealed for the first time that KIF22 depletion could restrain proliferation, glycolysis and accelerate apoptosis of melanoma cells by inactivating EGFR/STAT3 signaling." (PMID 37944197, 2023). "JQ1 was characterized by induction of inhibitory relationship linking regulators of inflammation (IFNG, IL17A, TGFB2), melanoma biological behavior (EGFR, WNT3A, TEADs, MRTFB), cell-cell interaction (CD44, CCN2), YAP pathway (LLGL2, NSUN6) and main transcriptional regulators (FOS, JUN, FOXM1)." (PMID 36397155, 2022). "Thus, EVs released by the metastatic melanoma cells stimulate the growth of the normal keratinocytes via the activation of EGFR and the PI3K/AKT/mTOR and MEK/ERK intracellular signaling pathways." (PMID 35327461, 2022).
melanoma (continued). "Outstanding response predictions for BRAF/MEK inhibitors are preferentially enriched in melanoma cell lines, while other drugs such as EGFR inhibitors exhibit cancer-type agnostic iGenSig scores, consistent with the tumor-type related clinical activities of these drugs." (PMID 35618721, 2022). "Since EGFR was found to be over-expressed in a number of cancer cell lines, including those from breast, colon, non-small cell lung, renal, melanoma, ovarian, and prostate cancers we selected EGFR as a potential target and the mechanism behind the anticancer activity of the title compounds." (PMID 36297760, 2022). "Additionally, the depletion of a negative regulator of EGFR protein degradation (ACK1) results in the accumulation of EGFR and melanoma cells which confers resistance to targeted therapy." (PMID 35565444, 2022). "Indeed, we showed that activation of SRC leads to the reactivation of the EGFR after its phosphorylation (Y845) in BRAFi‐resistant melanoma cell lines (Fig EV5A–C)." (PMID 36305167, 2022). "Thus, the aim of this work was to create a mouse syngeneic melanoma model that expresses a significant level of human EGFR." (PMID 36432639, 2022). "In our study, elevated EGFR levels are related to a poor prognosis of melanoma patients." (PMID 35692844, 2022). "The activation of the uPA/uPAR system has been reported to drives aerobic glycolysis (Warburg effect) in melanoma cell lines even in normoxic conditions, and this activation depends on the α5β1-integrin-mediated uPAR connection with EGFR with the engagement of the PI3K-mTOR-HIFα pathway." (PMID 36591282, 2022). "The cytotoxic effects of DSF-102 against human triple negative breast MDA-MB-231 and human colon HCT-15 cancer cells, overexpressing EGFR, as well as on human melanoma cells, poorly expressing EGFR, were also determined, to obtain preliminary data on the specificity of action of the compound." (PMID 35954311, 2022). "Thus, the aim of this study was to develop mouse syngeneic melanoma model that expresses human EGFR." (PMID 36432639, 2022). "Besides reactivating MAPK, PI3K/Akt and EGFR signaling have also been involved in BRAF inhibitor resistance in melanoma." (PMID 36210843, 2022). "Limited availability of EGFR strongly positive mouse tumorigenic cancer lines (and no such melanoma cells) hinders the use of this convenient variant for the next-step preliminary in vivo testing via in vitro screening EGFR-targeted agents." (PMID 36432639, 2022). "The direct role of AhR in regulating the phosphorylation of SRC (Y416) and EGFR (Y845) may promote together the acquisition of the aggressive/invasive EMT like phenotype of BRAFi‐resistant melanoma (Synopsis)." (PMID 36305167, 2022). "In addition, amplifications at EGFR, BRAF V600E, NRAS and KRAS loci, mutations of NRAS, KRAS and MAP2K1, and PTEN loss are often observed in resistant lesions of melanoma and CRC patients with treatment of combined RAF targeted therapies 85-87." (PMID 35966590, 2022). "As a result, we have successfully developed what is, to the best of our knowledge, the first mouse melanoma model with preserved in vivo expression of human EGFR, suitable for in vivo efficacy studies of EGFR-targeted drugs in syngeneic transplantable melanoma tumor setting." (PMID 36432639, 2022). "Notably, high expression of EGFR results in a slow-growth phenotype with melanoma cells, but EGFR turned into a cancer-promoting factor and contributed to the targeted therapy resistance to BRAF or MEK inhibitors." (PMID 35692844, 2022). "In addition, rosmarinic acid enhanced cisplatin sensitivity of melanoma cells through mediating the ADAM17/EGFR/AKT/GSK3β axis." (PMID 34516354, 2021). "EGFR expression is therefore only detectable in a subset of melanoma cells." (PMID 33916908, 2021).
melanoma (continued). "Furthermore, many of the cancer cell lines, including breast, colon, non-small cell lung, renal, melanoma, ovarian, and prostate cancer cell lines, have been found to express varying levels of EGFR; thus, it was worth testing their anti-EGFR activity." (PMID 34451604, 2021). "We have shown that LRIG1 is a conserved EGFR regulator that is lost in early melanoma development." (PMID 33947959, 2021). "Other studies showed that six out of 16 melanoma tumors acquired EGFR expression after the development of resistance to BRAF or MEK inhibitors, and acquired resistance was found with the overexpression of signaling receptors like EGFR, PDGFRβ, or MET that reactivation the MAPK pathway." (PMID 34360915, 2021). "In a recent study, Melanocyte Inducing Transcription Factor (MITF) and EGFR genes have shown the highest frequency of genomic amplification, with a lower rate in primary melanomas as compared to metastatic melanomas, considering both tumor tissues and cell lines." (PMID 34123788, 2021). "Within the “gene driver free” cohort, in addition to the ETV6→NTRK3 fusion positive LAC, we also detected three rearrangements in three independent melanoma patients: a rare EGFR ex26→LOC100996654 fusion, a BRAF intradomain duplication between ex10 and ex18 and a MET ex14 skipping." (PMID 34282766, 2021). "For EGFR, ChIP sequencing analyses revealed multiple MITF binding sites throughout the EGFR genomic region in the melanoma cell line 501Mel and few binding sites in Colo829 and SK-MEL-28 melanoma cells, implying a possible direct role of MITF in EGFR expression regulation." (PMID 33916908, 2021). "Therefore, additional research is required to properly characterize the EGFR/SDF-1/CXCR signaling axis in melanoma." (PMID 34067095, 2021). "Exosomes contain large dsDNA fragments spanning multiple genomic regions and harbor EGFR (T790M and L858R) 82 and BRAF (V600E) 83 gene mutations, proposing the possibility of tracing these mutations in plasma exosomes of NSCLC and/or melanoma patients through liquid biopsy." (PMID 34234872, 2021). "The present study shows that inhibition of SIRT2 (shRNA-mediated knockdown and pharmacological by thiomyristoyl) resulted in sensitization of melanoma cells to the widely used anticancer drug cisplatin, most likely by targeting EGFR stability and downstream signaling." (PMID 34068624, 2021). "Following BRAF or MEK inhibitor treatment, melanoma tumors had acquired EGFR expression." (PMID 34360915, 2021). "Therefore, we depleted LRIG1 in human melanoma cells (A375) by CRISPR/Cas9 technology and found that this caused EGFR and ERBB3 downregulation in A375 LRIG1 knockout cells 6 h following stimulation with EGF." (PMID 33786987, 2021). "A recent study on melanoma identified that low extracellular pH promoted anoikis resistance through an increased N-cadherin expression with an enhanced migrative ability through the activation of epidermal growth factor receptor (EGFR) and Akt pathways." (PMID 33854965, 2021). "EGFR autocrine loop is required for transformation by activated Ras in different mammalian cell systems, including fibroblasts, keratinocytes, intestinal epithelial cells, melanomas and pancreatic cells." (PMID 34411095, 2021). "In canine melanoma, little is known regarding EGFR expression and its role." (PMID 33664868, 2021). "Consequently, studies evidenced that about 89% of primary cutaneous melanomas and 91% of melanoma metastases show a high level of either EGF or EGFR expression, suggesting them as targets for therapy." (PMID 33918490, 2021). "In relation to this, further investigation was carried out which indicated that melittin prevents the invasion and migration of melanoma cells in a metastatic cell model, mainly though interference with F-actin reorganization and epidermal growth factor receptor (EGFR) activation." (PMID 34356743, 2021).
melanoma (continued). "Similarly, in a BRAFV600E melanoma model, treatment with vemurafenib was shown to upregulate EGFR expression to overcome the mitogen-activated protein kinase (MAPK) pathway inhibition in response to drug treatment." (PMID 33807785, 2021). "Further, Xmrk and EGFR may also modulate similar chemokine, extracellular matrix, oxidative stress, and microRNA signaling pathways in melanoma." (PMID 34067095, 2021). "We hypothesized that both low TMB-associated EGFR-mutant lung tumors and high TMB-associated melanoma present a repertoire of tumor-specific or tumor-associated antigen-derived peptides on HLA class I." (PMID 34391887, 2021). "In contrast to NSCLC, EGFR is not mutated in melanoma, but is rather induced, e.g., as a result from therapy stress." (PMID 33916908, 2021). "Additionally, combining EGFR antagonists to immunotherapy showed efficacy in a melanoma mouse model." (PMID 33918490, 2021). "Together, these results suggest that the necessity for EGFR activation in PI3K human melanoma signaling may depend on the specific melanoma subtype and that signaling homologies between Xmrk fish melanoma models and human skin cancer may not always occur." (PMID 34067095, 2021). "In melanoma, EGFR, HER3 and HER4 high expression was correlated with poor prognosis." (PMID 33918490, 2021). "The EGFR/SFK pathway was found to mediate resistance to vemurafenib treatment in BRAF-mutant melanoma, and BRAF and EGFR/SFK inhibition was reported to block the proliferation and invasion of these tumors, providing potentially effective therapeutic options for these patients." (PMID 33474634, 2021). "Mechanistically, LRG1 mediates melanoma cell invasiveness in an EGFR/STAT3-dependent manner." (PMID 34208965, 2021). "Similarly, tissue-specific targeting via the epidermal growth factor receptor (EGFR), or via a tumour marker like melanoma-associated high molecular weight antigen, have been developed with the assistance of dimeric antibody fragments (diabodies)." (PMID 34638863, 2021). "Myelosuppressive drugs upregulated HB-EGF and EGFR expression in melanoma cells." (PMID 34360915, 2021). "The uncontrolled activation of the MAPK signalling pathway in melanomas may be caused by overexpression or hyperactivation of growth factor receptors such as c-Met, c-KIT, and epidermal growth factor receptor (EGFR)." (PMID 34203771, 2021). "P124S is located in the MEK1 protein kinase domain and has previously been shown to confer resistance to BRAF- and MEK-inhibitor therapy in melanoma, but its role in EGFR-Ab resistance in CRC was unknown." (PMID 33322618, 2020). "The results suggested that FLG, DSG1, DSG3, IVL, and EGFR might play important roles and potentially be valuable in the prognosis and treatment of melanoma." (PMID 33178610, 2020). "It has also been observed that EGFR expression in different melanoma cell lines and their EVs may vary." (PMID 32886718, 2020). "Moreover, as deprivation of exogenous EGF was enough to trigger inhibition of EGFR signaling, production of EGFR-activating ligands in resistant melanoma cells was insufficient." (PMID 31936151, 2020). "However, the role of EGFR is not completely understood as a regulator or cancer promoter and initiator due to its essential functions in the biology of melanocytes and melanoma." (PMID 33171861, 2020). "It is known that EGFR expression is more pronounced in colon cells compare to melanoma that may explain the lower sensitivity of the investigated colon cell lines to MEK inhibition." (PMID 33081092, 2020). "This is the first time HER2, HER3, Her4, and EGFR are reported in canine melanoma." (PMID 31996230, 2020). "EGFR-directed treatment strategies were introduced in colorectal adenocarcinomas wild-type for NRAS and KRAS and BRAF inhibitor treatment finds application in BRAF V600E mutated malignant melanomas." (PMID 33227073, 2020).